HNRNPA1 (heterogeneous nuclear ribonucleoprotein A1)
Diseases named in the same sentence as HNRNPA1 in open-access papers (continued):
Sharing a sentence is not in itself a finding about the gene and the disease.
leukemia (4 papers, 2019 to 2022). A malignant (clonal) hematologic disorder, involving hematopoietic stem cells and characterized by the presence of primitive or atypical myeloid or lymphoid cells in the bone marrow and the blood. "Together, our findings suggest a novel mechanism of how HNRNPA1 promotes leukemia progression: by selectively sorting tumor suppressor miRNAs into exosomes." (PMID 31534508, 2019). "The study of Gao and colleagues demonstrated that HNRNPA1 (a type of RNA-binding proteins) -mediated exosomal transfer of miR-320 from leukemia cells to BMMSC is an important process of leukemia progression and could be a potential therapeutic target for CML." (PMID 35784717, 2022). "Collectively, these data demonstrate that HNRNPA1 functions importantly in the sorting of miR-320 into leukemic exosomes, and Imatinib might inhibit leukemia cell growth partially via interfering the pathway." (PMID 31534508, 2019). "Hence, heterogeneous nuclear ribonucleoprotein A1-mediated transfer of exosomal miR-320 from leukemia cells to BMSCs could be an important mediator of leukemia progression and a potential therapeutic target for chronic myelogenous leukemia." (PMID 35004702, 2021). "As leukemia stem cells (LSC) are the origin of CML, it is thus worthwhile to confirm whether the HNRNPA1 mediated miR-320 sorting into exosomes occurs in LSCs." (PMID 31534508, 2019).
melanoma (4 papers, 2017 to 2022). A malignant, usually aggressive tumor composed of atypical, neoplastic melanocytes. "At last, the concentration of estradiol which we chose was 10×10-13M because it was beneficial to hnRNPA1 expression in melanoma." (PMID 28035066, 2017). "Results indicated that silence of hnRNPA1 led to the increase of MDM2 at protein levels, which can be observed obviously in melanoma cells (P<0.05)." (PMID 28035066, 2017). "In a word, via increasing hnRNPA1 level and then reducing the expression of MDM2, estradiol prevented carcinogenesis in melanomas." (PMID 28035066, 2017). "In summary, the estradiol is a rationally anti-skin cancer agent that induces MDM2 down-regulation via enhanced hnRNPA1 expression, and controls the oncogenic activities of MDM2 in melanomas in vitro/vivo testing." (PMID 28035066, 2017). "Our data demonstrated that estradiol prevented proliferation, migration and EMT progression of melanomas in vitro by increasing the expression of hnRNPA1 and then influencing the level of MDM2 in melanomas." (PMID 28035066, 2017). "In the present work, we explored the translation control of MELOE‐1 and provide evidence that heterogeneous nuclear ribonucleoprotein A1 (hnRNP‐A1) binds to the MELOE‐1 IRES and acts as an IRES trans‐activating factor (ITAF) to promote the translation of MELOE‐1 in melanoma cells." (PMID 34418284, 2022). "Ectopic hnRNPA1 elicited thapsigargin-induced endoplasmic reticulum (ER) stress, promoted translation of specific melanoma-overexpressed antigen 1 (MELOE-1), and further enhanced recognition of melanoma cells by MELOE-1-specific T-cell clone, improving their immune efficacy." (PMID 35879279, 2022).
Paget disease (4 papers, 2021 to 2023). A malignant neoplasm composed of large cells with large nuclei, prominent nucleoli, and abundant pale cytoplasm (Paget cells). "The HNRNPA1 mutations are primarily detected in the subjects with inclusion body myopathy, Paget disease." (PMID 35964197, 2022).
Paget’s disease of bone (4 papers, 2014 to 2024). "For family E, WES in individual E:II:2 identified a known HNRNPA1 (c.785A>T; p.D262V) missense mutation, which was previously reported in a family with autosomal dominant myopathy and Paget’s disease of bone (PDB)." (PMID 34291734, 2021). "FTD in combination with inclusion body myopathy and Paget’s disease of bone in the patients or families strongly suggests mutations in the VCP, hnRNPA1, or MATR3 genes." (PMID 26213621, 2015).
COVID-19 (3 papers, 2021 to 2022). A disease caused by infection with severe acute respiratory syndrome coronavirus 2. "Other studies have shown a renoprotective role of linagliptin in animal models by modifying different signaling pathways (collagen type I homeostasis, HNRNPA1, YB-1, thymosin β4 and TGF- β1 and apolipoprotein C1), which could be also involved in the beneficial effect in COVID-19 patients." (PMID 35017617, 2022).
Crohn disease (3 papers, 2012 to 2020). A gastrointestinal disorder characterized by chronic inflammation involving all layers of the intestinal wall, noncaseating granulomas affecting the intestinal wall and regional lymph nodes, and transmural fibrosis. "In particular, mutations in hnRNPA1 associated to ALS, mutations in hnRNP D0/AUF1 identified in familiar cases of Crohn Disease and mutations in hnRNP DL causing limb-girdle muscular dystrophy 1G." (PMID 30642249, 2019). "siRNA silencing of NCL or HNRNPA1, alone or together, increased CD39 mRNA levels and MFI in Treg and Th17 cells of Crohn’s disease patients." (PMID 33208731, 2020). "No significant changes were observed in CD39 mRNA levels and MFI following NCL and HNRNPA1 silencing in Treg and Th17 cells obtained from healthy subjects and in the levels of CD39-AS RNA in Treg and Th17 cells from both Crohn’s disease patients and healthy subjects." (PMID 33208731, 2020). "Importantly, silencing of NCL, HNRNPA1, or both boosted the suppressive function of Treg derived from Crohn’s disease patients; such an effect was not noted in Treg derived from healthy controls." (PMID 33208731, 2020). "Consistent with this, silencing of NCL and HNRNPA1 resulted in upregulation of CD39 only in cells that expressed high levels of CD39-AS RNA like Treg and Th17 cells derived from Crohn’s disease patients but not from healthy subjects." (PMID 33208731, 2020).
fragile X-associated tremor/ataxia syndrome (3 papers, 2016 to 2024). Fragile X-associated tremor/ataxia syndrome (FXTAS) is a rare neurodegenerative disorder characterized by adult-onset progressive intention tremor and gait ataxia. "The interactors hnRNPA1, hnRNPA2B1, Matr3, FMRP and Prkra have previously been associated with neurodegenerative diseases (ALS, multisystem proteinopathy, fragile X-associated tremor/ataxia syndrome (FXTAS), fragile-X syndrome (FXS) and dystonia parkisonism)." (PMID 27164932, 2016).
glioblastoma (3 papers, 2018 to 2025). The most malignant astrocytic tumor (WHO grade IV). "In a study on glioblastoma, MA unveiled inhibitory effects on GSK-3β and its downstream pathways, splicing factors, PTBP1, SF2/ASF, and hnRNPA1, as well as anti-apoptotic regulators." (PMID 39863145, 2025).
ovarian carcinoma (3 papers, 2017 to 2022). A malignant neoplasm originating from the surface ovarian epithelium. "Although hnRNPA1 was highly expressed in ovarian cancer tissue compared with normal tissues, it has been reported that hnRNPA1 showed a low expression in drug-resistant ovarian cancer cells." (PMID 32296635, 2020). "Our findings reported suggest that inhibition of hnRNPA1-miRNA interactions is key to overcoming acquired resistance to DXT in ovarian cancer cells." (PMID 28904816, 2017). "The observation that low hnRNPA1 expression was correlated with high K-RAS expression prompted us to elucidate how the biological functions of the hnRNPA1 protein are affected by miRNAs to better understand the protein’s role in ovarian cancer." (PMID 28904816, 2017). "Published work has suggested that inhibition of miR-25-3p might be effective in the treatment of ovarian cancer, but this inhibition has not been associated with the miR-25-3p and/or miR-15a-5p-hnRNPA1 loop." (PMID 28904816, 2017). "In response to an A2780 ovarian cancer cell line treated with 9-methoxycanthine-6-one, it was noted that 3 proteins, namely GAPDH, HNRNPA1 and PKM, suppressed and interfered with the anti-apoptotic protein, BCL-XL." (PMID 35163852, 2022). "We therefore carried out a comparative analysis of Drosha, hnRNPA1 and K-RAS expression, using the Affymetrix platform RNA Array and western blotting in HeyA8 and HeyA8-MDR ovarian cancer cell lines." (PMID 28904816, 2017). "We selected the chemoresistant ovarian cancer cell lines SKOV3-TR and HeyA8-MDR for further studies because of their high hnRNPA1 expression and in vivo tumorigenicity." (PMID 28904816, 2017).
Parkinson disease (3 papers, 2014 to 2022). A progressive degenerative disorder of the central nervous system characterized by loss of dopamine producing neurons in the substantia nigra and the presence of Lewy bodies in the substantia nigra and locus coeruleus. "The HNRNPA1 N50S carrier shows behavioral/psychiatric symptom and parkinsonism." (PMID 35964197, 2022). "HNRNPA1 is involved in protein translation, whereas ATG4B regulates AMPK signaling and energy homeostasis, and PSMC4 physically interacts with AMPK and is involved in Parkinson’s disease." (PMID 31097295, 2019).
psoriasis (3 papers, 2015 to 2025). An autoimmune condition characterized by red, well-delineated plaques with silvery scales that are usually on the extensor surfaces and scalp. "Several autoantigens have been implicated in psoriasis, amongst which are keratin 13 (K13), heterogeneous nuclear ribonucleoprotein-A1 (hnRNP-A1), and Rab coupling protein isoform 3 (FLJ00294) (RAB11FIP1), although the epidermal autoantigens have not been conclusively identified." (PMID 26339139, 2015). "Notably, autoantibodies against K13, heterogeneous nuclear ribonucleoprotein A1 (hnRNPA1), K17, and Rab coupling protein isoform 3 (FLJ00294) have been identified in psoriasis patients." (PMID 41009795, 2025).
steatosis (3 papers, 2019 to 2025). Increased lipid within the cytoplasm of cells. "As a result of the interplay between lncRNA H19, hnRNPA1 protein, PPARγ, and miR-130a, it can be concluded that H19 is one of the most important lncRNAs in the formation of fatty liver and steatosis." (PMID 33622377, 2021). "It has been suggested that short time repression of the lncSHGL/hnRNPA1/CaM axis is probably advantageous for increased fasting gluconeogenesis and can be a strategy for type-2 dialethic Mellitus and steatosis treatment." (PMID 33622377, 2021). "Restoration of hepatic lncSHGL has been found to improve hyperglycemia, insulin resistance (IR), and steatosis in obese diabetic mice, suggesting that activating the lncSHGL/hnRNPA1 axis could be a potential strategy for the treatment of T2DM and steatosis." (PMID 40076814, 2025). "Mechanistic studies have found that lncSHGL recruits heterogeneous nuclear ribonucleoprotein A1 (hnRNPA1), activates the phosphatidylinositol 3-kinase (PI3K)/Akt pathway, and inhibits the mTOR / SREBP-1C pathway, thus ameliorating hyperglycemia and steatosis in obese mice." (PMID 30931332, 2019).
atherosclerosis (2 papers, 2017 to 2024). A disease characterized by the build-up of fatty material and calcium deposition in the arterial wall resulting in partial or complete occlusion of the arterial lumen. "Finally, we have also provided some preliminary but clear evidence to suggest a role of hnRNPA1/miR-124/IQGAP1 regulatory axis in human angiographic restenosis or atherosclerosis." (PMID 28912364, 2017). "HNRNPA1 is a regulator of vascular smooth muscle cell function and neointimal hyperplasia, i.e., the proliferation and migration of vascular smooth muscle cells in the innermost layer of the arteries, which results in thickening of the arterial wall and atherosclerosis." (PMID 39187864, 2024).
breast tumors (2 papers, 2014 to 2018). "A similar pattern emerged upon analysis of breast tumours from 194 patients whereby upregulation of BCL-XL (R2 = 0.8587, P = 0.028862) and decrease in cytoplasmic hnRNPA1 (R2 = 0.9793, P = 0.001522) staining correlated with an increase in S6K2 staining." (PMID 25324306, 2014).
colorectal adenocarcinoma (2 papers, 2022 to 2024). The most common type of colorectal carcinoma. "Collectively, high expressions of hnRNPA1, hnRNPK, hnRNPR, and hnRNPU were significantly associated with better OS rates for colorectal adenocarcinoma patients." (PMID 35875075, 2022). "Furthermore, we demonstrated that high expressions of hnRNPA1, hnRNPK, hnRNPR, and hnRNPU were associated with better overall survival rates for colorectal adenocarcinoma patients." (PMID 35875075, 2022). "Our study identified a significant elevation in hnRNPA1 expression in different cancers such as colorectal adenocarcinoma (COAD), diffuse large B-cell lymphoma (DLBC), and liver hepatocellular carcinoma (LIHC)." (PMID 39834948, 2024). "Immunohistochemical staining revealed that hnRNPA1, hnRNPA2B1, hnRNPC, hnRNPK, hnRNPR, and hnRNPU are overexpressed in colorectal adenocarcinoma." (PMID 35875075, 2022). "In this study, we illustrated that the expression of hnRNPA1 was elevated in colorectal adenocarcinoma tissues, which was in line with the previous findings." (PMID 35875075, 2022). "The results showed that hnRNPA1, hnRNPK, hnRNPR, and hnRNPU in the nucleus had higher expressions in colorectal adenocarcinoma cells compared with FHC cells." (PMID 35875075, 2022). "In colorectal adenocarcinoma, hnRNPA1 was identified as a potential biomarker and contributed to tumor growth by enhancing aerobic glycolysis." (PMID 35875075, 2022). "By using IHC staining of 10 human colorectal adenocarcinoma specimens, we confirmed that hnRNPA1, hnRNPA2B1, hnRNPC, hnRNPK, hnRNPR, and hnRNPU were mainly localized in the nucleus and had higher expressions in colorectal adenocarcinoma tissues compared with adjacent normal tissues (ANT)." (PMID 35875075, 2022). "However, high expression of hnRNPA1 predicted better OS rates in colorectal adenocarcinoma patients, suggesting that hnRNPA1 might be an antitumor factor in tumorigenesis." (PMID 35875075, 2022). "The interaction between hnRNPK and hnRNPA1/R/U proteins was confirmed by Co-IP in HCT116 cells, ascertaining the existence of hnRNPK/A1/R/U complex in colorectal adenocarcinoma cells." (PMID 35875075, 2022).
diabetes (2 papers, 2020 to 2021). "Through the PPI network screening, it was found that 5 key genes (YWHAZ, HNRNPA1, HSPA8, HSP90AA1, and HSPA5) obtained through protein interactions may provide new ideas for the treatment of diabetes." (PMID 32851081, 2020).
endometrial cancer (2 papers, 2022 to 2023). Primary or metastatic malignant neoplasm involving the endometrium (mucous membrane that lines the endometrial cavity). "Esculetin directly binds to hnRNPA1 and decreases the concentration of hnRNPA1 in endometrial cancer cells, and it downregulates the levels of BCL-XL and XIAP expression, resulting in apoptosis and an arrest in proliferation." (PMID 36838831, 2023). "Esculetin is a coumarin derivative that suppresses endometrial cancer proliferation and induces apoptosis by downregulating the BCLXL and XIAP via hnRNPA1." (PMID 35264951, 2022).
esophageal cancer (2 papers, 2021 to 2024). A primary or metastatic malignant neoplasm involving the esophagus. "In the proteomics database of 124 patients with esophageal cancer, tumors showed higher hnRNPA1 expression than normal tissue." (PMID 38810697, 2024).
gastric tumor (2 papers, 2020 to 2021). "In the current study, hnRNPA1 has been screened out by MS for its up-regulation in gastric tumor tissues." (PMID 32106859, 2020). "In addition, hnRNPA1 has been shown to be upregulated in gastric tumor tissues by MS." (PMID 34845198, 2021).
Hepatic steatosis (2 papers, 2022 to 2025). Steatosis is a term used to denote lipid accumulation within hepatocytes. "Loss of hnRNPA1 in murine skeletal muscle was shown to exacerbate IR and hepatic steatosis under HFD conditions." (PMID 40392981, 2025). "These combined effects independently suppress gluconeogenesis and lipogenesis in hepatocytes, offering a promising therapeutic strategy for treating hepatic steatosis via the lncSHGL/hnRNPA1 regulatory axis." (PMID 40392981, 2025).
HIV-1 infection (2 papers, 2015 to 2019). The type species of lentivirus and the etiologic agent of acquired immunodeficiency syndrome (AIDS). "It has been previously demonstrated that HIV-1 infection induces cytoplasmic retention of RBPs harboring prion-like domains, including hnRNPA1 and hnRNPD." (PMID 31695598, 2019). "We find that pseudogene HNRNPA3P6, its parent gene HNRNPA3 and a close paralog of the parent gene HNRNPA1 are under-expressed in HIV-1 infection." (PMID 26426037, 2015).
Hyperglycemia (2 papers, 2019 to 2021). An increased concentration of glucose in the blood. "This lncRNA suppressed fatty liver accumulation and hyperglycemia in high-fat diet mice by recruiting the heterogeneous nuclear ribonucleoprotein A1 (Hnrnpa1) to increase the rate of calmodulin (Cam) protein translation." (PMID 35052690, 2021).
Insulin resistance (2 papers, 2020 to 2021). Increased resistance towards insulin, that is, diminished effectiveness of insulin in reducing blood glucose levels. "Conditional knockout of hnRNPA1 in mouse muscle promotes insulin resistance and more generally disrupts glucose metabolism, a parallel to GO enrichments for metabolic terms we see in DE genes in Hrb87F-IR." (PMID 34685485, 2021).
lupus (2 papers, 2016 to 2021). "The second part, a number of versatile RBPs [such as YBX1, Ago2, MVP, HuR, heterogeneous nuclear ribonucleoprotein A1 (hnRNPA1), lupus La protein, and EWI-2] have a positive influence on the encapsulation of one or several sEV-miRNAs." (PMID 34222256, 2021). "Heterogeneous nuclear ribonucleoprotein A1 (HNRNPA1) has previously been associated with RA, systemic lupus erythematosus and mixed connective tissue diseases and other rheumatic diseases." (PMID 27729089, 2016).
lymph node metastasis (2 papers, 2016 to 2020). "Moderate to strong hnRNPA1 immunostaining was strongly linked to adverse tumor features including high classical and quantitative Gleason score, lymph node metastasis, advanced tumor stage, positive surgical margin, and early biochemical recurrence (p < 0.0001 each)." (PMID 32417965, 2020). "In CR-adenocarcinoma, the median level of HNRNPA1 was significantly higher in well-differentiated type (7.0 vs. 5.0; p = 0.020), no lymph node metastasis (7.0 vs. 4.3; p = 0.003), or low (≤II)-stage (7.0 vs. 4.3; p = 0.003) groups than in the other groups." (PMID 27282379, 2016).
myelodysplastic syndrome (2 papers, 2022 to 2024). A clonal hematopoietic disorder characterized by dysplasia and ineffective hematopoiesis in one or more of the hematopoietic cell lines. "For example, splicing factor 3b subunit 1 (SF3B1) mutations have been described in myelodysplastic syndrome (MDS), and deregulated heterogeneous nuclear ribonucleoprotein A1 (hnRNPA1) expression has occurred in solid cancers." (PMID 36230624, 2022). "Increased TRAF6 signaling is linked to myelodysplastic syndrome (MDS), where TRAF6 overexpression in mouse HSPCs results in MDS-like features, such as cytopenia, by regulating exon specification through TRAF6-mediated ubiquitination of RNA-binding protein hnRNPA1." (PMID 38609495, 2024).
myotonic dystrophy (2 papers, 2020 to 2021). An inherited progressive disorder affecting the muscles. "hnRNPA1 is also abnormally expressed in myotonic dystrophy, where similar to CELF1, it promotes fetal splicing patterns and antagonizes MBNL activity." (PMID 34685485, 2021).
Obesity (2 papers, 2022 to 2026). Accumulation of substantial excess body fat. "In conditions of HNRNPA1 deficiency, as observed in obesity, the regulatory mechanism is disrupted, resulting in a significant enhancement of CCL2 protein synthesis and secretion by adipocytes." (PMID 41596407, 2026). "HNRNPA1 expression is markedly reduced in white adipose tissue depots of obese human subjects and established murine models of obesity." (PMID 41596407, 2026). "Our recent research also showed that celastrol accelerated the degradation of hnRNPA1 by directly binding with it, and modulated hnRNPA1-IκBα-NF-κB-TNF-α pathway to play a role in obesity-depression comorbidity." (PMID 35656110, 2022).